LATS1 (large tumor suppressor kinase 1)
Diseases named in the same sentence as LATS1 in open-access papers (continued):
Sharing a sentence is not in itself a finding about the gene and the disease.
tumor (327 papers, 2008 to 2026). "In this study, our focus was on investigating the potential role of LATS1/2 in the antigen processing and presentation pathway, which is often associated with tumor immune evasion." (PMID 38383447, 2024). "The results showed that LATS1/2 loss accelerated tumor growth more significantly in immunocompetent mice than in immunodeficient mice, highlighting the critical role of the host immune system in LATS1/2-mediated anti-tumor effect." (PMID 38383447, 2024). "Among all the examined tumor types, LATS1/2 genes exhibited the highest prevalence of mutations and genomic deletions in EC." (PMID 38383447, 2024). "The Hippo signaling components LATS1/2, each encoding a tumor-suppressive serine or threonine-protein kinase, phosphorylate their effectors TAZ/YAP, causing YAP1 and TAZ’s cytoplasmic retention and destabilization." (PMID 39531326, 2024). "Tubular-specific genetic dual depletion of YAP/TAZ in Lats1/2-deficient mice, conversely, mitigated tumor formation, directly demonstrating YAP/TAZ involvement in renal tumorigenesis downstream of Lats 1/2 deficiency." (PMID 39123485, 2024). "LATS1/2 deletion in cancer cells also induces strong immune responses, overwhelming any growth advantage gained by the loss of LATS1/2 and leading to strong inhibition of tumor growth in vivo." (PMID 38566194, 2024). "A total of 9 LATS1 mutations occurred in approximately 9.1% (9/99) of the tumor specimens, including 3 truncating mutations, 8 missense mutations." (PMID 38383447, 2024). "The current study found that LATS1/2 deficiency enhanced tumor immunogenicity, leading to tumor destruction through an enhanced antitumor immune response." (PMID 37548821, 2023). "The tumor suppressor activity of the Hippo pathway leads to phosphorylation of the YAP/TAZ proteins by LATS1/2 kinases, causing their cytoplasmic retention and degradation." (PMID 37773066, 2023). "Similar to in vitro cell experiments, overexpression of circXRN2 significantly reduced the tumor growth rate, and knockdown of LATS1 significantly attenuated the inhibitory effect caused by circXRN2." (PMID 37684641, 2023). "YAP/TAZ pathway is key downstream component of Hippo signaling pathway, which can be activated and phosphorylated by upstream MST1/2 and LATS1/2, leading to the inhibition of function, causing cell proliferation and tumor growth." (PMID 38071381, 2023). "While increased nuclear YAP and TAZ are correlated with less aggressive tumors, higher cytoplasmic TAZ, TEAD4 and LATS1 are associated with high-grade and more advanced stage neoplasms." (PMID 37509515, 2023). "LATS1/2 expression is downregulated in breast cancer and is associated with aggressive phenotypes such as increased tumor size, lymph node metastases, and poor prognosis." (PMID 36443319, 2022). "Such EVs from the LATS1/2 deficient tumor cell lines induced tumor-specific adaptive immune responses." (PMID 33935791, 2021). "Conversely, Moroishi and collaborators demonstrated that LATS1-2-deficient tumor cells showed reduced in vivo tumor growth, while in vitro YAP/TAZ hyperactivation promoted tumoral expansion." (PMID 34205830, 2021). "LATS1 (Large Tumor Suppressor Gene) is a Ser/Thr kinase associated with the Tumor Suppressor pathway called the Hippo-LATS/Warts pathway that represses tumor outgrowth by controlling cell proliferation, cell growth, and cell death." (PMID 33773564, 2021). "Defects in Hippo pathways that included RASSF7 amplification and NF2 or LATS1/2 mutations were present in 50% of tumours and were accompanied by micromolar responses to the YAP1 inhibitor Verteporfin." (PMID 34580349, 2021). "LATS1 suppressed the expression of glioma-associated oncogene-1 (Gli1), and LATS1's tumor-suppressive actions in CRC are dependent on Gli1." (PMID 35003351, 2021). "Reduced melanin content in LATS1 knocked down tumors was associated with increased tumor growth, pointing to melanin’s protective role in this process." (PMID 33803640, 2021).
tumor (continued). "Mechanically, LATS1/2-deficient tumor cells secreted robust level of nucleic-acid-rich extracellular vesicles, which activated IFN-I response via TLR-MYD88/TRIF signaling and enhanced antitumor immune responses." (PMID 32174922, 2020). "We tested if deficiency in YAP1 phosphoregulation by LATS1/2 is sufficient to cause tumour formation by conditionally knocking out Lats1 and Lats2, in NEX-Cre lineage." (PMID 32404936, 2020). "Loss of Lats1/2 promotes tumor cell growth in vitro, but inhibits tumor growth in murine tumor models." (PMID 32019579, 2020). "Consistent with this, a previous report demonstrated that, although high-dose verteporfin alone suppressed Lats1/2-deficient tumor cell growth in vivo relative to vehicle, it increased risk of mortality due to toxicity." (PMID 32960816, 2020). "We report that loss of Lats1 alone is sufficient to drive anterior and intermediate lobe tumour formation." (PMID 30912742, 2019). "ITCH negatively regulates the Hippo tumor suppressor pathway by building a K48-linked polyubiquitin chain on of the serine/threonine kinase LATS1, a tumor growth inhibitor that induces G2-M arrest and apoptosis." (PMID 30229450, 2019). "Loss of both Lats1 and Lats2, encoding potent tumour suppressors, leads to dramatic tissue overgrowth during gestation, revealing a function for these enzymes in restricting growth during pituitary development." (PMID 30912742, 2019). "MST1/2 and LATS1/2, upstream regulators of the Hippo tumor-suppressing signaling, are frequently deleted and mutated, whereas the downstream effectors, YAP and WWTR1 (encoding TAZ), are frequently amplified." (PMID 30401982, 2019). "Loss of LATS1 heterozygosity has been reported in a range of human tumours leading to an increase in YAP/TAZ protein levels." (PMID 30912742, 2019). "Similar to Lats2 deletion, conditional knockout of Lats1 caused a significant increase in tumor burden relative to WT-PyMT littermate controls." (PMID 30456386, 2018). "Various types of tumor arise in hypomorphic Mob1 mouse, and phenotypes of liver-specific Mob1-deficient mice are similar to Lats1/2-knockout liver." (PMID 28035075, 2017). "LATS1 gene has been investigated in only one study reporting inactivating mutations in 47 of 293 (16%) BCCs, with 24% of the mutations being truncating, consistent with the tumor suppressor role of LATS1." (PMID 29165358, 2017). "Our present findings provide the demonstration that LATS1 expression is frequently decreased in GC tissues, and loss of LATS1 expression is associated with tumor invasion, poor prognosis and recurrence in GC patients." (PMID 26921249, 2016). "For example, the RASSF1A (RAS association domain family 1A) tumour suppressor can trigger apoptotic signalling through MST1/2-mediated activation of LATS1/2 and NDR1/2." (PMID 27213455, 2016). "While the functional significance of some of these mutations have been experimentally tested in vivo, results reported here further support that LATS1/2 act normally as tumor suppressors and loss of their functions contributes to human cancer development." (PMID 25482410, 2015). "In the Catalogue of Somatic Mutation in Cancer (COSMIC) database, 101 non-synonymous LATS1 somatic mutations have been identified from 9183 unique human tumor samples." (PMID 25482410, 2015). "Loss of LATS1 leads to a variety of tumour types including soft tissue sarcomas, leukaemia, as well as breast, prostate, lung and oesophageal cancers." (PMID 25712415, 2015). "H-warts (LATS1) is a key player in mitosis in mammalian cells and loss of its function disrupts normal cell cycle regulation possibly leading to tumor development." (PMID 18419822, 2008). "In this way, we identified the significance of LATS1 mutation in early tumor evolution." (PMID 40247187, 2025).
tumor (continued). "The association between Hsp90 and Lats1, an essential component of the Hippo signaling pathway, reduces Lats1 activity, ultimately deactivating the entire Hippo signaling pathway, therefore affecting tumor cell behavior." (PMID 40612677, 2025). "In addition, bortezomib (an inhibitor of the proteasome) restored the expression level of LATS1 protein in circXRN2-deficient tumor cells." (PMID 37684641, 2023). "Loss of LATS1/2 in tumor cells inhibits tumor growth and enhances anti-tumor immune response." (PMID 37853413, 2023). "However, another study demonstrated that the loss of LATS1/2 triggers anti-tumor immune responses by releasing nucleic-acid-rich extracellular vesicles." (PMID 36294681, 2022). "On a hard surface, the Hippo pathway is involved in the proliferation of tumor cells, consisting of three main components: large tumor suppressor 1/2 (LATS1/2), yes-associated transcriptional regulator/tafazzin (YAP/TAZ) and mammalian Ste20-like kinases 1/2 (MST1/2)." (PMID 35267698, 2022). "LATS1/2 loss in these studies enhances tumour immunogenicity, which promotes anti-tumor immune responses and tumour regression leading to a reduction in tumorigenicity invivo, suggesting that the Hippo pathway plays a complex role in the involvement of the immune response to oncogenesis." (PMID 35119068, 2022). "Since MST1/2 and LATS1/2 core constitute a regulatory part of the Hippo signaling associated with a tumor suppressor effect, the transcriptional cofactors YAP/TAZ associated with TEAD transcription factors represent the terminal effectors of this pathway and play a pro-oncogenic role." (PMID 33477668, 2021). "Due to genomic deletions or mutations (relatively rare), epigenetic silencing, or transcriptional and post-transcriptional regulations, tumor suppressors LATS1/2 and MST1/2 could undergo loss-of-function." (PMID 33467099, 2021). "As hypothesized, loss of Nf1 significantly increased the tumor burden of H7;Lats1/2mut3;Nf1mut mice." (PMID 32960816, 2020). "Moreover, the loss of two tumour suppressor genes Breast Cancer Susceptibility Gene 2 (BRCA2) or the LATS1 tumour suppressor is accompanied by cytokinesis defects, suggesting a role for these tumour suppressors during cytokinesis." (PMID 26491220, 2015). "However, our in silico analysis provides supporting evidence that LATS1/2 mutations drive human tumor development based on the following observations: 1) Cancer mutations in hLATS1/2 do not appear to be random mutations." (PMID 25482410, 2015). "In the present study, we hypothesized that decreased expression of LATS1 was associated with tumor metastasis and the poor prognosis and recurrence in GC patients and overexpression of LATS1 suppressed growth and metastasis in GC cells through inhibition of the YAP signaling." (PMID 26921249, 2016). "The PMEPA1-a isoform bypasses the tumor-suppressive Hippo pathway by inhibiting LATS1/2 kinase activity." (PMID 41932868, 2026). "LATS1/2 deletion that activated YAP/TAZ in mouse cancer cells enhanced anti-tumor adaptive immunity and led to tumor destruction." (PMID 40940864, 2025). "Immunohistochemical analysis of LATS1 expression in 80 tumor samples revealed that LATS1 was downregulated in 45% of CvSCC cases." (PMID 41256331, 2025). "LATS1/2 deletion in immunocompetent mouse models paradoxically enhances anti-tumor immunity, highlighting context-dependent outcomes." (PMID 41373772, 2025). "LATS1, a crucial tumor suppressor within the Hippo signaling pathway, has recently been recognized as a novel actin-binding protein and a regulator of the cell-cycle." (PMID 40478495, 2025). "It is well known that the level of tumor immunogenicity affects the survival of tumor cells, and it has been found that inhibition of LATS1/2 kinase in the Hippo pathway seems to enhance tumor immunogenicity and thus can achieve the purpose of LC treatment." (PMID 40557151, 2025).
tumor (continued). "Another YAP/TAZ regulatory axis, the canonical Hippo pathway involves MST1/2 and LATS1/2 which are integral upstream core kinase components of the Hippo pathway and serve as crucial tumor-suppressors." (PMID 39936032, 2025). "Upstream tumor suppressors, including MST1, LATS1/2, and FAT1/2/3/4, frequently undergo deletions or mutations, whereas downstream oncogenes such as YAP1, WWTR1, and TEAD1/2/3/4 are upregulated." (PMID 41256331, 2025). "Inactivation of tumour suppressor genes LATS1/2 or increased YAP/TAZ expression disrupts downstream targets, causing cancer cells to develop resistance against anti-cancer drugs." (PMID 41614824, 2025). "YAP plays a central role in tumor cell proliferation and invasion, Calotropin promotes LATS1 degradation, leading to YAP dephosphorylation and nuclear localization." (PMID 40612350, 2025). "Within the Hippo pathway, MST1/2 and LATS1/2 act as tumor suppressors by inhibiting PD-L1 expression, whereas the downstream effectors YAP and TAZ promote PD-L1 upregulation, thereby impairing T-cell function and facilitating immune escape." (PMID 41256331, 2025). "SNHG9 interaction with the PA of LATS1 plays a tumor-promoting role by affecting LATS1 phosphorylation by MOB1 and the subsequent phosphorylation of YAP." (PMID 40801625, 2025). "YAP and TAZ act as potent oncogenic drivers, whereas MST1/2 and LATS1/2 function as tumor suppressors." (PMID 41373772, 2025). "Specifically, LATS1 exerts tumor-suppressive functions by increasing p27 levels, decreasing cyclin E and matrix metalloproteinase-9 (MMP-9), and promoting YAP phosphorylation." (PMID 41256331, 2025). "Genetic or pharmacological re‐expression of tumor suppressors within the Hippo pathway, including activating LATS1/2 kinases and MST1/2 (mammalian Ste20‐like kinases), has also been explored." (PMID 40895190, 2025). "When LATS1/2 are aberrantly repressed or mutated, their ability to inhibit YAP/TAZ is compromised, leading to unchecked cell proliferation and tumor growth." (PMID 39757214, 2025). "Previous studies have confirmed that NEDD4 is involved in the ubiquitination and degradation of the large tumor suppressor kinase 1 (LATS1) in tumor cells, thereby affecting the activity of the Hippo pathway." (PMID 39890782, 2025). "Simultaneously, restoring the expression of tumor suppressors like LATS1/2 or MST1/2 can re‐establish normal Hippo signaling, thereby counteracting oncogenic YAP/TAZ activity." (PMID 40895190, 2025). "To determine the signaling pathways involved in the anti-fibrotic effect of ZLD1039, we focused on the Hippo signaling pathway, particularly due to the pivotal role of LATS1 as a key tumor suppressor within this pathway." (PMID 40478495, 2025). "O-GlcNAcylation of yes-associated protein (YAP) represses its interaction with large tumor suppressor gene 1 (LATS1), resulting in its transactivation and tumor progression." (PMID 40416363, 2025). "This activation subsequently enhances the phosphorylation of YAP/TAZ by LATS1/2, leading to the cytoplasmic retention of these pro-proliferative transcriptional co-activators and ultimately inhibiting aberrant tumor cell growth." (PMID 40486910, 2025). "SPOP facilitates tumorigenesis by targeting and promoting the degradation of tumor suppressors like LATS1, PTEN, SETD2, and others, thus disrupting important signaling pathways such as the Hippo, PI3K/Akt, and cell cycle regulation pathways." (PMID 40521202, 2025). "Large tumor suppressors 1 and 2 (LATS1/2), as a key component of the Hippo signaling pathway, prevent tumor development by maintaining tissue homeostasis and inhibiting cellular hyperproliferation." (PMID 39174509, 2024).
tumor (continued). "Immunohistochemistry (IHC) assessments of YAP1 and Lats1 protein levels in 54 human tumor sections of ccRCC and normal renal tissues revealed prominent YAP1 nuclear immunoreactivity in the proximal tubules of ccRCC tumors compared to the normal kidney." (PMID 39123485, 2024). "Proteomic data from the Clinical Proteomic Tumor Analysis Consortium further confirmed the lower expression of LATS1 protein in EC specimens (p = 0.0278)." (PMID 38383447, 2024). "Loss of function or genetic mutations in Hippo kinases like NF2 and LATS1/2 leads to the activation of YAP, fostering positive interactions with other pathways and driving tumor progression." (PMID 38396367, 2024). "LATS1/2 exert tumor-suppressive functions by phosphorylating and inactivating the Yes-associated protein (YAP) and the transcriptional co-activator with PDZ-binding motif (TAZ), which are transcriptional co-activators promoting cell proliferation and survival." (PMID 38383447, 2024). "The profound decrease in MHC-I expression observed in LATS1/2 KO cells suggests a potential weakening of anti-tumor immunity." (PMID 38383447, 2024). "We postulated that LATS1/2 loss reduces MHC-I expression and impairs MHC-I-mediated antigen presentation in tumor cells, leading to a decrease in CD8+ T cells infiltration in allograft tumors." (PMID 38383447, 2024). "The Hippo pathway exerts tumor suppressive effects via its core members, including MST1/2, large tumor suppressor kinase 1/2 (LATS1/2) and the transcriptional coactivator Yes-associated protein (YAP)." (PMID 38650929, 2024). "Hippo signaling controlled the expression of genes of the MHC-I antigen processing and presentation pathway, and loss of LATS1 and LATS2, critical kinases required for Hippo signaling activation, favors tumor immune evasion through decreasing MHC-I expression." (PMID 39545415, 2024). "HCG11 acts as a tumor suppressor and suppresses tumor growth in LUAD by promoting Large Tumor Suppressor Kinase 1 (LATS1)." (PMID 38351139, 2024). "They discovered that inactivation of LATS1/2 in tumor cells strongly suppresses tumor growth in immune-competent but not immune-compromised mice, which is caused by the induction of anti-tumor immune responses." (PMID 38920690, 2024). "Despite the well-established tumor-suppressive functions of LATS1/2, a comprehensive exploration of genetic alterations in human cancers is currently lacking." (PMID 38383447, 2024). "Another study showed that LATS1/2 deletion in tumor-surrounding cells eliminated cancer cells through cell competition in mice." (PMID 38566194, 2024). "According to research by Xu's group, decreasing YTHDF2 increases LATS1's ability to limit tumour growth while high YTHDF2 expression in BRCA cells encourages the creation of tumours." (PMID 39135292, 2024). "Abnormal expression of has-miR-424-5p enhances the proliferation and invasion of tumor cells by targeting LATS1 gene." (PMID 39600941, 2024). "The upstream components of the Hippo pathway, MST1/2 and LATS1/2, function as tumor suppressors by promoting the binding of YAP/TAZ and 14-3-3 through phosphorylation, leading to their cytoplasmic localization and degradation." (PMID 38499647, 2024). "In this study, we have introduced a new tumor immune evasion mechanism utilized by EC that involves the engagement of LATS1/2." (PMID 38383447, 2024). "Stiff 3D culture wasassociated with the downregulation of tumor suppressors (LATS1, BCAR3, CDKN2C), as well as theupregulation of cancer-associated genes (RAC3)." (PMID 38466617, 2024). "For instance, fusions of oncogenic proteins TAZ, YAP1, and HIPK2 preserve their tumor-promoting function, while fusions of tumor suppressors, such as NF2, LATS1, FAT1, PTPN14, DCHS2, TAOK1, and TAOK3, results in loss of their function." (PMID 38499647, 2024). "LATS1 encodes a serine/threonine kinase that negatively regulates YAP, and exhibits anti-tumor activity by restricting cell proliferation or promoting apoptosis." (PMID 37151881, 2023).